CD4 (CD4 molecule)
Diseases named in the same sentence as CD4 in open-access papers (continued):
Sharing a sentence is not in itself a finding about the gene and the disease.
lymphopenia (continued). "Based on our results, we cannot conclude if there is a pathogenetic link between arginase-expressing macrophages and lymphopenia seen in CD4+ T cells and specifically in Th2-like cells in TMS patients during relapse." (PMID 36761741, 2023). "Multiple lymphocytes populations, such as CD8+T, CD4+T, γδT and NK cells, were affected by the lymphopenia phenomenon with T-cells preferentially impacted in acute necrotizing encephalopathy." (PMID 37848421, 2023). "Phenotyping often shows CD8 lymphopenia with a normal or mildly decreased CD4 count, with the latter typically improving with time." (PMID 36648576, 2023). "Sepsis is characterized by upregulation of CD4 + and CD8 + T cells, T helper 17 cells, and regulatory T cells, lymphopenia, and loss of immune function." (PMID 36855207, 2023). "In spite of causing lymphopenia, SARS-CoV-2 is capable of eliciting IgG and IgA antibody responses, as well as CD4+ (predominantly Th1) and CD8+ T cell responses in the majority of infected individuals with mild symptoms." (PMID 37762435, 2023). "The researchers enrolled a total of 335 patients from two hospitals in one southern Chinese city and found that pre-operative lymphopenia, particularly CD4+ T lymphopenia, correlated with poor prognosis via apoptosis." (PMID 36920980, 2023). "Another key feature of severe COVID-19 patients was lymphopenia, since reduced numbers of CD4+ and CD8+ T cells, B cells, and NK cells were commonly observed in those patients." (PMID 37762435, 2023). "This CD4+ lymphopenia was equally marked in patients with SCI LCP (SCI LCP = 0.859 [0.671–1.108] cells/mL, *** p = 0.001)." (PMID 38139422, 2023). "A hallmark of this dysregulated scenario is the lymphopenia with paradoxical CD8+ and CD4+ T cell hyperactivation or exhaustion, which mediate immunopathology or immunosuppression." (PMID 37809093, 2023). "Lymphopenia and reductions in CD4+ T-cells, CD8+ T-cells, B-cells, and natural killer cells were observed in more than 70% of patients with no coronary pneumonia, with depletion of CD4+ and CD8+ T-cells being the most pronounced." (PMID 38146366, 2023). "Both B-cell lymphopenia with a normal T-cell count and CD4+ T-cell lymphopenia with a normal B-cell count has been reported." (PMID 38116000, 2023). "All three homozygous LCK-mutated patients presented with prominent CD4 and progressive CD8 lymphopenia as well as increased proportions of γδT cells." (PMID 38112969, 2023). "In CDV infection, acute-phase lymphopenia is characterized by a depletion of T-helper (CD4+), cytotoxic T (CD8+), and B (CD21+) cells in the peripheral blood." (PMID 37958115, 2023). "In patients with disseminated NTM infection, idiopathic CD4 lymphocytopenia and anti-IFN-γ autoantibody-positive immunodeficiency can be coexisted." (PMID 36717786, 2023). "In contrast, the CD4+ T-cell lymphopenia seen with HIV occurs within the context of subgrades tracking disequilibrium (IHG-IVa, IHG-IVb)." (PMID 37311745, 2023). "Impaired immune surveillance simultaneously occurs due to HIV-induced CD4 lymphopenia and ineffective CD8 responses." (PMID 37476029, 2023). "Rap1 deficiency caused lymphopenia-induced proliferation (LIP) of naïve CD4+ cells, resulting in an increased proportion of effector CD4+ cells." (PMID 39132043, 2023). "The heterogeneity and spatial segregation of effector function posits that PLZF+CD4+ T cells are composed of a combination of lymphopenia-induced, memory phenotype cells as well as antigen-experienced memory T cells." (PMID 37856221, 2023). "T-cell count was below normal ranges in 2 out of 6 patients even though CD4+ lymphopenia was observed only in patient P2." (PMID 37755605, 2023). "Significant CD4+ lymphopenia was also quantified in patients with SCI LCP (SCI LCP = 0.527 [0.473–0.322] cells/mL, *** p = 0.000)." (PMID 38139422, 2023).
lymphopenia (continued). "There were 37.0–58.1% with lymphopenia (<1000/mm3), 33.3–45.2% had low CD4 cell counts (<500/mm3), and 74.1–96.8% had low B cell counts (<100/mm3) in the non-seroconversion group." (PMID 36851338, 2023). "Negative SARS-CoV-2 IGRA results were associated with increased disease severity, higher peripheral lymphocytopenia, and decreased T cell and CD4+ T cell counts." (PMID 37855635, 2023). "It is an infection usually identified in patients with impaired T‐cell immunity, particularly CD4+ lymphopenia." (PMID 37273666, 2023). "Type C (malignant) cases also had severe lymphopenia, but in the other types a mere 15% had CD4+ cell <250/μL." (PMID 37371700, 2023). "CD4 lymphopenia engenders inadequate production of high-affinity antibodies, and is associated with high-risk HPV progression." (PMID 37476029, 2023). "This is the first prospective study to address the prognostic value of CD4+ T lymphopenia in NSCLC with long-term follow-up of over 10 years." (PMID 35546670, 2022). "We identified CD4+ T lymphopenia as an independent prognostic factor in local/loco-regional stages of NSCLC and CD4+ T lymphopenia is also associated with a high risk of death, regardless of NSCLC clinical stage." (PMID 35546670, 2022). "In a recent study, we demonstrated that the PLA2G1B/cofactor system is an inhibitor of CD4 T cells that is involved in the induction of anergy and lymphopenia of CD4 T cells in HIV-infected patients." (PMID 35392090, 2022). "Lymphopenia with a deficit of CD4+ T cells and a higher number of CD8+ T cells correlate with mortality in severe SARS-CoV-2 infection." (PMID 35891232, 2022). "In the whole cohort, median OS was better for patients with CD4 TL counts > 500/μL compared with those who had CD4 + T lymphopenia (21.7 versus 16.1 months, respectively, HR: 1.616 [95% CI: 1.1–2.36], p = 0.012)." (PMID 35546670, 2022). "Severely ill patients exhibit macrophage overreaction (also known as macrophage activation syndrome MAS) and lymphocytopenia in effective lymphocytes, including neutrophils, CD4+ T cells, and NK cells." (PMID 36091053, 2022). "Alemtuzumab is highly effective in the treatment of patients with relapsing multiple sclerosis (PwRMS) and selectively targets the CD52 antigen, with a consequent profound lymphopenia, particularly of CD4+ T lymphocytes." (PMID 35296069, 2022). "Lymphocytopenia was a common finding in almost all patients, and they frequently had CD4+ T cell counts less than 400 cells/mm3." (PMID 35736068, 2022). "As a feedback response to lymphopenia, serum IL-7 concentration was also negatively related to the number of T cells, CD4+ and CD8+ cells, highlighting the link between lymphopenia and higher IL-7 levels in SARS-CoV-2 infection." (PMID 35958594, 2022). "Here, we found that metastatic patients were more frequently affected by CD4 lymphopenia than patients with localized disease." (PMID 35546670, 2022). "Compared with the non-PJP patients, the indicators of P. jirovecii infection, such as elevated 1,3-ß-D-glucan, LDH and CD4+ T lymphopenia, were more common in the PJP group." (PMID 35782118, 2022). "The LN patients were characterized by CD4+ T cells lymphopenia, affecting both naïve and memory subsets, with a preserved thymic function." (PMID 36430418, 2022). "The patient's immunological phenotype included marked B cell lymphopenia with reduced pre-switch and switch memory B cells, decreased CD4+ and CD8+ naïve T cells, elevated CD4+ and CD8+ TEMRA cells, and abnormal T cell activation and proliferation." (PMID 35464398, 2022). "The CD4+ T lymphopenia appears to be an independent prognostic factor for poor overall survival in local/loco-regional NSCLC." (PMID 35546670, 2022). "Our previous clinical study has also confirmed that lymphopenia characterized by the reduction of both CD4+ and CD8+ T cells in peripheral blood is a common feature among influenza-infected patients, and linked to the worse outcome (not yet published)." (PMID 35317717, 2022).
lymphopenia (continued). "From a pathological point of view, it has been reported that people with HIV and SARS-CoV-2 co-infection had higher levels of inflammatory markers, lymphopenia and lower CD4+ T cell counts." (PMID 35972980, 2022). "Calves infected with Att-S74-T3Bo developed a moderate but significant lymphocytopenia of CD4+ T cells at day 7 post-infection." (PMID 36466866, 2022). "Dexamethasone use has been associated with significant lymphopenia in patients with GBM, especially for CD4 T cells." (PMID 35716311, 2022). "As regards adaptive immunity, sepsis-induced apoptosis leads to lymphopenia in patients with septic shock and this process involves all types of T cells (CD4, CD8 and Natural Killer), except for regulatory T cells, which retain their function." (PMID 36358327, 2022). "This is the case of the lymphopenia on CD4 T cells we observed in SARS-CoV2 exposed newborns in cord blood that significantly increased after six months." (PMID 35911743, 2022). "There is a paucity of data regarding the prognostic influence of peripheral blood CD4+ T lymphopenia in NSCLC." (PMID 35546670, 2022). "Conventional fractionation for various solid tumors produced profound lymphopenia and reduced both CD4+ and CD8+ T cells; this effect was sustained for at least 6 months." (PMID 35597954, 2022). "Toward this, literature search revealed a case of a previously healthy man who developed tumefactive MS and peripheral immune cell profiling revealed naïve lymphopenia (low CD4 and CD8 levels) (Supplementary Excel Files, Sheet-4, Supplementary References)." (PMID 35418930, 2022). "CD4+ T lymphopenia was significantly more frequently observed in elderly patients (p = 0.053), and in patients with performance status ≥2 (p = 0.041)." (PMID 35546670, 2022). "Another paper by Patel and colleagues described the application of multiple PML therapeutics in a patient with CD4+ lymphopenia." (PMID 34994851, 2022). "This lymphopenia involved CD4+, CD8+ and NK cells and was more pronounced with a Gram-positive infection." (PMID 36358327, 2022). "In patients with CD4 lymphopenia and CID feature, HLA-DR expression is assessed on B cells as they are the most abundant antigen presenting cells (APCs) in peripheral blood." (PMID 35655284, 2022). "Patients with CD4+ T lymphopenia showed lower overall survival than those with CD4+ T lymphocytes count > 500/μL (median overall survival (OS) 16.1 versus 21.7 months, hazard ratio (HR): 1.616 [95% CI: 1.1–2.36], p = 0.012)." (PMID 35546670, 2022). "As regards adaptive immunity, sepsis leads to lymphopenia and immunosuppression in patients with septic shock; this process involves all types of T cells (CD4, CD8 and Natural Killer), except for regulatory T cells, which retain their function." (PMID 36358327, 2022). "In summary, the results for the treatment of PML with interleukins are promising especially if PML is based on CD4+ lymphopenia." (PMID 34994851, 2022). "As expected, the majority of allo-HSCT recipients displayed persistent CD4 T cell lymphopenia up to 1-year post-transplantation while most of them reconstituted normal levels of CD8 T cells and NK cells by 3-months and 1-month post-allo-HSCT respectively." (PMID 36713419, 2022). "Sepsis development is also associated with significant lymphopenia, which is characterized by decreased counts of CD8+ and CD4+ T cells, B cells and natural killer (NK) cells." (PMID 36203606, 2022). "A study on memory CD4+ T-cell proliferation during recovery from septic lymphopenia showed that bone marrow is the primary site of CD4+ T-cell homing and proliferation during sepsis-induced immunosuppression." (PMID 36209190, 2022). "We observed a decrease in CD3+ T cell frequency, in both CD4+ and CD8+ subpopulations, in COVID19 patients compared with HDs reflecting clinical lymphopenia, and an increase in the CD4+ regulatory T (Treg) cell population." (PMID 34987646, 2022).
lymphopenia (continued). "All animals experienced marked lymphopenia between day 3 and day 12, affecting CD4+ and CD8+ T cells, as well as B cells and NK cells." (PMID 35437094, 2022). "There is a paucity of data regarding the prognostic influence of peripheral blood CD4+ T lymphopenia in non-small cell lung cancer (NSCLC)." (PMID 35546670, 2022). "Inducible tyrosine kinase (ITK) deficiency is associated with progressive CD4+T-cell and NKT-cell lymphopenia, and hypogammaglobulinemia resulting in EBV viremia and immune dysregulation leading to massive LP." (PMID 35603189, 2022). "Acute lymphopenia, particularly low CD4 + T lymphocytes, is related to poorer clinical outcomes in ST-segment elevated MI patients." (PMID 35964050, 2022). "On the other hand, apoptosis-induced CD4+ and CD8+ T lymphopenia has been associated with severe COVID." (PMID 36605446, 2022). "CID Patients having CD4 lymphopenia are tested for HLA-DR, DOCK8 expression and T cell maturation and recent thymic immigrants (CD4+CD45RA+CD31+)." (PMID 35655284, 2022). "Att-S74-T3Bo-infected calves developed an early significant monocytosis, neutropenia and CD4+ lymphopenia in peripheral blood." (PMID 36466866, 2022). "The administration of anti-inflammatory effectors, such as IL-7, was shown to reverse lymphopenia and increase CD4+/CD8+ T-cell proliferation in septic shock." (PMID 36680144, 2022). "Lymphopenia induced homeostatic proliferation is followed by clonal attrition; with only 19% of dominant CD4 (p <0.025) and 13% of dominant CD8 (p <0.005) clones from the pre-transplant repertoire detected at 36 months." (PMID 35197974, 2022). "In whole cohort, CD4+ T lymphopenia (< 500/μL) and CD8+ T lymphopenia (< 224/μL) were observed in 28.4 and 29.6% of patients respectively." (PMID 35546670, 2022). "Idiopathic CD4 Lymphopenia is a heterogeneous condition, recognized in the late 20th century, with a wide spectrum of presentations, requiring a high index of suspicion to avoid misdiagnosing the condition." (PMID 36291470, 2022). "LN patients were characterized by pronounced lymphopenia, mainly affecting the CD4 compartment, with a concurrent reduction in the naïve, central and effector memory subsets compared to the HCs." (PMID 36430418, 2022). "Anti-CD28dAb reversed lymphopenia-induced differentiation of memory CD4+ T cells in the spleen and lymph node compared to TCD alone." (PMID 36761170, 2022). "Most patients display a decreased HLA-DR expression on monocyte (mHLA-DR) (median of 6,793) and a marked CD4+ T lymphopenia (median of 275 CD4+ cells/μl) compared with normal values (>15,000 AB/C for mHLA-DR; 336–1,126 CD4+ cells/μl)." (PMID 36045686, 2022). "Taken into the context of CD4+ T cell lymphopenia that occurs in severe COVID, it is unclear how the frequencies of circulating SARS-CoV-2-specific cells per million CD4+ T cells relate to absolute cell number." (PMID 35857584, 2022). "A study involving 1099 patients in China demonstrated that patients with severe COVID‐19 presented with peripheral lymphocytopenia and hyperactivated CD4+ and CD8+ T cells." (PMID 35578891, 2022). "As many other authors have reported, global lymphopenia, including CD4+ and CD8+ T cells, reflects the depletion and deterioration of the immune system." (PMID 35203509, 2022). "Previous renal transplant cohorts have reported prolonged CD4 lymphopenia in some patients following transplant-related immunosuppression." (PMID 36661655, 2022). "Immune phenotypes included CD4 T-cell lymphopenia, elevated B cells, inverted CD4/CD8 ratios, and elevated αβDNTs." (PMID 35145548, 2022). "Untreated HIV infection is characterized by CD4+ T-cell lymphopenia, which becomes critical when CD4+ T-cell numbers are below 200cells/μl." (PMID 36483556, 2022).
lymphopenia (continued). "There was a trend towards an increased frequency of CD4+ T lymphopenia (56%) in metastatic patients versus 44% in patients with localized NSCLC (p = 0.24)." (PMID 35546670, 2022). "Active PLA2G1B was initially described for its role in the intestinal absorption of lipids before our recent demonstration of its role in CD4 T-cell anergy and CD4 T-cell lymphopenia in HIV-infected patients." (PMID 35392090, 2022). "As regards adaptive immunity, sepsis-induced apoptosis leads to lymphopenia in patients with septic shock and this process involves all types of T cells (CD4, CD8 and Natural Killer), except for regulatory T cells, favoring immunosuppression." (PMID 36358327, 2022). "The most recognized risk factors for developing PJP in non-HIV patients included immunosuppressive therapy, such as glucocorticoid use, and CD4+ lymphocytopenia." (PMID 35736068, 2022). "The most common treatment-related AEs included decreased CD4+ lymphocyte counts, lymphopenia, fatigue, and musculoskeletal toxicity." (PMID 35267638, 2022). "The propensity of CD4 T cells to die is positively correlated with T cell lymphopenia and higher levels of CXCL10, both markers of disease severity." (PMID 35066575, 2022). "This is the first prospective study addressing the prognostic value of CD4+ T lymphopenia in NSCLC with long-term follow-up." (PMID 35546670, 2022). "The CD3+CD4+ lymphopenia led to a significantly lower CD4/CD8-ratio (0.9 ± 0.6 versus 2.1 ± 1.1, P<0.001) in DLBCL patients." (PMID 36700229, 2022). "Only CD4+ T lymphopenia was included in the multivariate analysis because among the immunological parameters, this variable was most strongly associated with survival in univariate analysis." (PMID 35546670, 2022). "Unexpectedly, aged G‐CSF−/− mice exhibited an expansion of CD4+ T cells, and contrary to the well‐established CD4+ T cell lymphopenia observed in aged Lyn−/− mice, Lyn−/−G‐CSF−/− mice had normal numbers of CD4+ T cells, comparable to C57BL/6 controls." (PMID 33960699, 2021). "This includes patients with Good’s syndrome, a combination of thymoma, CD4 lymphopenia and hypogammaglobulinemia." (PMID 34367167, 2021). "Although CVID is a disease of defective B cell maturation, various reports have associated CVID with T cell compartment abnormalities, such as CD4+ T cell lymphopenia with reduced subset counts of naive CD4+ T cells and naive CD8+ T cells." (PMID 34362140, 2021). "Previously suggested mechanisms of naïve CD4+ lymphopenia during chronic HCV disease include immune cellular anatomic redistribution following portal hypertension and splenic sequestration, but this does not explain the selective loss of naïve CD4+ T cells." (PMID 35062255, 2021). "Additional clinical laboratory assays performed on a subset of patients showed that, in accordance with lymphopenia, the absolute counts of CD4 and CD8 T-cells and B-cells were diminished." (PMID 34632327, 2021). "The most common pre-existing conditions in surveyed subjects were idiopathic CD4 + lymphopenia (14%) and diabetes mellitus (7%)." (PMID 33574462, 2021). "Lymphopenia is a main feature of COVID-19 infection, affecting CD4+ and CD8+ T cells as well as B lymphocytes, and is more pronounced in severely ill patients." (PMID 34925369, 2021). "An early study reported that patients with DM can have lymphocytopenia, manifested as lower peripheral blood CD4+ and CD8+ T-cell and B-cell absolute counts before the initial treatment, and significant increase in lymphocyte count after treatment." (PMID 35111785, 2021). "As expected, we found a lower fraction of T cells in the patient compared to the controls, which was mainly attributed to selective CD4+ T cell lymphopenia." (PMID 34427831, 2021). "This condition phenocopies Gsnor−/− mice lymphopenia and is in line with results obtained in Jurkat and CD4+ T cells, in which pharmacological inhibition of ATM is associated with cell death and reduction of proliferation upon stimulation." (PMID 33245190, 2021).